TLR2 (toll like receptor 2)
Diseases named in the same sentence as TLR2 in open-access papers (continued):
Sharing a sentence is not in itself a finding about the gene and the disease.
amyotrophic lateral sclerosis (3 papers, 2018 to 2022). Amyotrophic lateral sclerosis (ALS) is a neurodegenerative disease characterized by progressive muscular paralysis reflecting degeneration of motor neurons in the primary motor cortex, corticospinal tracts, brainstem and spinal cord. "Although the role of TLR1 in neurodegenerative diseases is not yet clear, TLR2 involvement in microglial activation has been increasingly demonstrated in amyotrophic lateral sclerosis, MS, and AD." (PMID 35408945, 2022).
aneurysm (3 papers, 2016 to 2022). Bulging or ballooning in an area of an artery secondary to arterial wall weakening. "A significant upregulation of the TLR2 gene and greater expression of TLR2 protein in ruptured aneurysms has been observed in patients with intracranial aneurysms." (PMID 34200356, 2021). "Our study revealed that, in the majority of cases, aneurysm rupture leads to the release of soluble TLR2 and 4 forms into the CSF." (PMID 27223696, 2016). "For example, the interaction between toll-like receptor 2 (TLR2) and its endogenous ligand promotes the development of AAA, and the expression of RAGE and its ligand AGE is highly elevated in human aneurysm specimens." (PMID 35874515, 2022). "It has been suggested that the enhancement of TNF-α expression via the activation of TLRs, particularly TLR2 and TLR6, in aneurysm walls may contribute to neurological deficits after SAH." (PMID 34200356, 2021).
Atrophy (3 papers, 2009 to 2019). Any weakening or degeneration, especially through lack of use. "Therefore, we analyzed TLR2 expression during chronic IgA nephropathy which is also associated with interstitial fibrosis, tubular atrophy, and interstitial inflammation." (PMID 19479087, 2009). "In summary, the present study demonstrated that the genomic deletion of TLR2 induced impaired neurobehavioral function, WMD and loss of neurons, brain atrophy, and the activation of astrocytes." (PMID 31509519, 2019). "Extensive renal atrophy in end-stage hydronephrotic kidneys made it however impossible to phenotype TLR2-positive cells on histologic sections." (PMID 19479087, 2009).
autoimmune thyroid disease (3 papers, 2019 to 2022). Inflammatory disease of the thyroid gland due to autoimmune responses leading to lymphocytic infiltration of the gland. "In the context of autoimmune thyroid disease, expression of TLR2 and TLR4 positive T-cells and B-cells were higher in the peripheral blood of Graves’s disease patients compared to normal controls, and the proportion significantly decreases after obtaining euthyroid status." (PMID 36521376, 2022).
bronchiectasis (3 papers, 2021 to 2025). Segmental, irreversible dilation of the bronchial tree resulting in the accumulation of secretions which leads to obstruction. "To investigate this, we recruited 25 CPA patients and 25 controls with bronchiectasis, isolating immune cells from peripheral blood for detailed flow cytometric phenotyping at resting state and after ex vivo stimulation with the TLR2/Dectin-1 agonist Zymosan." (PMID 40503945, 2025). "TLR2, which recognizes i.a. zymosan and peptidoglycan (PGN), was significantly downregulated on sputum cells in both PCD and bronchiectasis." (PMID 36528664, 2022). "By mapping drug targets to disease targets, we identified 51 common targets, including IL10, TLR2, STAT3, IL6, and CXCL8, which served to indicate putative pathways whereby BMGLF could be used to treat bronchiectasis." (PMID 33488758, 2021).
brucellosis (3 papers, 2013 to 2017). Brucellosis is a bacterial infection that spreads from animals to people via unpasteurized dairy products or by exposure to contaminated animal products or infected animals. "We also found that the expression of TLR-2 (CD282) and TLR-4 (CD284) on all three monocyte subsets, particularly on the CD14++CD16− monocyte subset, increased in brucellosis patients compared with HC." (PMID 28659924, 2017). "In addition, the authors reported that TLR6 (but not TLR2) is required for the in vivo control of the bacteria in the murine model of brucellosis, and that murine DCs lacking TLR2 or TLR6 are unable to produce of TNF-α or IL-12." (PMID 23805193, 2013).
cardiac arrest (3 papers, 2013 to 2022). Cessation of breathing and/or cardiac function. "Further studies are necessary to elucidate the underlying mechanism and subsequently to further establish TLR2 inhibition as a potential innovative therapeutic approach of reducing mortality and morbidity after cardiac arrest and cardiopulmonary resuscitation." (PMID 24066159, 2013). "We suggest that other but also specific TLR2-related mechanisms are responsible for the beneficial effects of TLR2-deficiency in our animal model of cardiac arrest and resuscitation, however further studies are needed to resolve these mechanisms." (PMID 24066159, 2013). "In the present study, we investigated the effects of TLR2 pharmacological blockade by an inhibiting antibody as well as genetic TLR2 deficiency on survival and neurofunctional outcome after cardiac arrest (CA) and cardiopulmonary resuscitation (CPR) in mice." (PMID 24066159, 2013). "Compared to the control group, we observed significant upregulation of surface PRR TLR2 in the early phase after cardiac arrest, which was subsequently downregulated in the later phase." (PMID 27260481, 2016). "In analysis of time-dependent expression of monocyte mRNA in patients after cardiac arrest, significantly higher levels of TLR2, TLR4, IRAK3, NLRP3, and IL1B were observed in patients in the early hours after ROSC compared to the later phase." (PMID 27260481, 2016). "The notion that TLR2 might exhibit an important role in PCAS is further supported by a recent study where the administration of a TLR2 inhibiting antibody or genetic TLR2 deficiency improved survival and neurological function in mice after circulatory arrest." (PMID 27260481, 2016). "Thus, TLR2 inhibition could provide a novel therapeutic approach for reducing mortality and morbidity after cardiac arrest and cardiopulmonary resuscitation." (PMID 24066159, 2013). "Nonsurvivors at 30 days had significantly lower mRNA levels of TLR2, IRAK3, IRAK4, NLRP3 and CASP1 in the late phase following cardiac arrest." (PMID 27260481, 2016). "On a functional level, we observed a pronounced and sustained decrease in inflammatory cytokine release after TLR2 and TLR4 activation in patients after cardiac arrest ex vivo." (PMID 27260481, 2016). "Monocyte TLR2, TLR4, IRAK3, IRAK4, NLRP3, PYCARD and IL1B were initially upregulated in patients following cardiac arrest." (PMID 27260481, 2016). "We observed significant positive correlation between both TLR2 and IRAK4 mRNA transcript levels and dosage of norepinephrine to maintain a mean arterial blood pressure ≥80 mmHg in the early phase after cardiac arrest." (PMID 27260481, 2016). "In this study, we provide evidence for the activation of TLR2 and TLR4 in immediate survivors of cardiac arrest and describe the involvement of the NLRP3 inflammasome in the modulation of the subsequent systemic inflammatory response to global IRI caused by temporary circulatory arrest." (PMID 27260481, 2016). "Serum lactate levels at the time of blood sampling were significantly positively correlated with TLR2 (rs 0.570; p = 0.001), TLR4 (rs 0.369; p = 0.045), IRAK3 (rs 0.569; p = 0.001), and IRAK4 (rs 0.413; p = 0.029) monocyte mRNA levels in the early phase after cardiac arrest." (PMID 27260481, 2016).
childhood asthma (3 papers, 2013 to 2016). "Toll-like receptor 2, toll-like receptor 6, toll-like receptor 9, and toll-like receptor 10 appear to have some association with childhood asthma in Caucasians." (PMID 23496969, 2013). "For TLR2, rs4696480, rs3804099, rs3804100, and rs1898830 showed association with childhood asthma in a number of studies, but not in others." (PMID 23496969, 2013).
chronic heart failure (3 papers, 2011 to 2023). "Indeed, while TLRs expression is enhanced in CF monocytes, fluvastatin dose-dependently inhibits monocyte TLR4 and TLR2 expressions in whole blood from patients with chronic heart failure." (PMID 21826199, 2011).
colorectal tumors (3 papers, 2010 to 2020). "Mice deficient in TLR2 developed significantly more and larger colorectal tumors than their WT controls." (PMID 20885960, 2010). "However, TLR2−/− colorectal neoplasms displayed more distorted glands with regions of increased disorganization and cribriform structures indicative of a higher grade dysplasia (i.e. carcinoma in situ)." (PMID 20885960, 2010).
diabetic retinopathy (3 papers, 2013 to 2020). "A variety of physiologic abnormalities that have been implicated in the pathogenesis of diabetic retinopathy failed to develop in retinas of diabetics lacking TLR2/4, further implicating the TLR/MyD88 system in the pathogenesis of diabetic retinopathy." (PMID 23874797, 2013).
diffuse cutaneous Leishmaniasis (3 papers, 2016 to 2025). A form of LEISHMANIASIS, CUTANEOUS caused by Leishmania aethiopica in Ethiopia and Kenya, L. pifanoi in Venezuela, L. braziliensis in South America, and L. mexicana in Central America. "An important NK-cell inhibition with reduced TNF-α, IFN-γ and TLR2 expression had previously been identified in patients with diffuse cutaneous leishmaniasis (DCL) infected with Leishmania mexicana." (PMID 27031998, 2016). "It has been reported that patients with diffuse cutaneous leishmaniasis exhibited a reduced number of NK cells, lower levels of cytokines, such as IFN-γ, and diminished TLR expression, as is the case of TLR1, TLR2, and TLR6." (PMID 39963187, 2025).
dry eye (3 papers, 2011 to 2023). "In this study, we explored the expression of TLR2, as well as cytokines related to the TLR2–NF-κB signaling pathway, in dry eye associated with cGVHD." (PMID 22025895, 2011). "In conclusion, this is the first report to suggest that TLR2 and NF-κB expression is upregulated in dry eye associated with cGVHD and that this upregulation results in the significant generation of proinflammatory factor TNF-α." (PMID 22025895, 2011). "To explore the molecular mechanisms underlying the induction of dry eye symptoms, we analyzed the expression of TLR2 and the related downstream cytokines in peripheral blood." (PMID 22025895, 2011). "This preliminary study highlighted the potential role of TLR2 signaling in dry eye associated with cGVHD." (PMID 22025895, 2011). "The findings relating to the activation of the TLR2 signaling pathway in systemic inflammation will provide new insight into the inflammatory process of dry eye associated with cGVHD." (PMID 22025895, 2011). "Exploring molecular mechanisms of TNF-α generation via the TLR2–NF-κB signaling pathway should be quite useful for developing therapeutic approaches to combat dry eye associated with cGVHD." (PMID 22025895, 2011). "We are currently engaged in establishing a cGVHD model in TLR2 knockout mice to elucidate the molecular mechanism underlying the induction of cytokines/chemokines by TLR2 in dry eye associated with cGVHD." (PMID 22025895, 2011). "The TLR2-mediated NF–κB signaling pathway is activated in dry eye associated with cGVHD and contributes to the inflammatory state, which may predict the onset and progression of dry eye associated with cGVHD." (PMID 22025895, 2011). "The aim of this study was to explore whether the TLR2-mediated nuclear factor-kappa B (NF-κB) signaling pathway contributes to the inflammatory process of dry eye associated with cGVHD." (PMID 22025895, 2011). "The TLR2–NF-κB signaling pathway contributes to the inflammatory state, which may predict the onset and progression of dry eye associated with cGVHD." (PMID 22025895, 2011). "Thus, it is reasonable to conclude that TLR2–NF-κB signaling is activated in dry eye associated with cGVHD." (PMID 22025895, 2011). "Thus, we hypothesized that the inflammatory process in dry eye associated with cGVHD might be mediated in part by activation of the immune pathway through TLR2." (PMID 22025895, 2011). "Real-time PCR results revealed that TLR2 expression showed a marked increase in patients with dry eye related to cGVHD (2.48±2.35 versus 1.03±0.51, p=0.019)." (PMID 22025895, 2011). "The PCR analysis (1.91±1.94 versus 0.88±0.18, p=0.001) showed that NF-κB, the downstream gene of the TLR2 signaling pathway, was augmented in dry eye related to cGVHD." (PMID 22025895, 2011). "Our results showed that TLR2 signaling was significantly activated in these patients, suggesting that TLR2 contributes to the inflammatory state of dry eye secondary to cGVHD." (PMID 22025895, 2011). "In this study, we measured and analyzed alterations in the major components of TLR2 signaling in patients with dry eye related to cGVHD." (PMID 22025895, 2011). "TLR2 mRNA in the peripheral blood from patients with dry eye related to cGVHD increased significantly compared with the controls." (PMID 22025895, 2011). "Especially, TLR2 expression was significantly correlated with the dry eye profile such as OSDI scores and Schirmer’s test in these patients." (PMID 22025895, 2011). "Our results pointed to the upregulated expression of TLR2 and NF-κB, which efficiently trigger a cytokine storm and lead to the inflammatory response in patients with dry eye related to cGVHD." (PMID 22025895, 2011). "As mentioned in Section 2, PG, in the form of DMPG, which also inhibits HSPB4-induced TLR2 activation, is already present in an ophthalmic solution used to treat dry eye, indicating a good safety profile in this organ and stability in commercially available topical formulations." (PMID 36982926, 2023).
dry eye (continued). "Therefore, in this study we focused on TLR2 to research the role of innate immunity in dry eye related to chronic GVHD." (PMID 22025895, 2011). "However, we found that TLR2 and its downstream targeted molecules were remarkably upregulated in patients with dry eye related to cGVHD." (PMID 22025895, 2011). "Importantly, the TLR2 level was strongly correlated with the OSDI and the Schirmer’s test (r=0.565, p=0.010<0.05; r=0.564, p=0.016<0.05) in dry eye related to cGVHD compared with the controls." (PMID 22025895, 2011).
epilepsy (3 papers, 2022 to 2025). A brain disorder characterized by episodes of abnormally increased neuronal discharge resulting in transient episodes of sensory or motor neurological dysfunction, or psychic dysfunction. "TLR2, 3, and 4 have been described in cortical neurons and, for TLR4, a seizure-promoting role in epilepsies associated with inflammation has been shown." (PMID 35507634, 2022). "In our study, the TLR2 gene expression level was significantly higher in the epilepsy group." (PMID 39046369, 2024). "We performed Western blot analysis to measure TLR2, TLR4, NF-κB, and TNF-α protein levels in primary human cells derived from fresh surgically resected tissue samples of patients with HGG, LGG, and epilepsy." (PMID 40809181, 2025). "The signalling pathway in epilepsy may be activated by HMGB1, TLR4 and TLR2, which is considered to increase the level of proinflammatory cytokines." (PMID 39046369, 2024). "After binding to TLR2, TLR4 or RAGE, HMGB1 can trigger the activation of cytokines and affect downstream inflammatory factors that play an important role in modulating neuronal excitability, which can lead to the development of epilepsy." (PMID 39046369, 2024). "The signalling pathway in epilepsy may be activated by HMGB1, TLR4, and TLR2, which are considered to increase the level of proinflammatory cytokines." (PMID 39046369, 2024).
Erythema (3 papers, 2018 to 2025). Redness of the skin, caused by hyperemia of the capillaries in the lower layers of the skin. "Innate immune activation leads to upregulation of keratinocyte-derived toll-like receptor 2 (TLR2) promoting the expression of the antimicrobial peptide cathelicidin, which is subsequently activated to bioactive LL-37 by kallikrein 5 (KLK-5) protease, leading to erythema and angiogenesis." (PMID 40410272, 2025).
Fever (3 papers, 2020 to 2024). Body temperature elevated above the normal range. "TLR2 causes the release of cytokines in a different cell type that delivers fever-inducing signals to AH/POA and induces fever." (PMID 37046199, 2024).
glaucoma (3 papers, 2016 to 2025). Increased pressure in the eyeball due to obstruction of the outflow of aqueous humor. "The aim was to analyze the association of the TLR2 (rs5743708), TLR3 (rs3775291), TLR4 (rs4986790, rs4986791) and TLR6 (rs5743810) polymorphisms with primary open-angle glaucoma in patients of Western Siberia." (PMID 40144379, 2025). "Retinal microglia upregulate TLR expression as an early response to glaucomatous damage, polymorphisms in both TLR2 and TLR4 are risk alleles for glaucoma, and deletion of Tlr4 in mice reduces RGC death after optic nerve damage and ischemia-reperfusion." (PMID 27126275, 2016). "Studies of anatomy have reported elevated levels of TLR2, TLR3, and TLR4 in microglia and astrocytes in the retina of glaucoma patients." (PMID 34561506, 2021).
glomerulonephritis (3 papers, 2013 to 2022). A renal disorder characterized by damage in the glomeruli. "As such, a pathogen-induced TLR activation has been implicated in glomerulonephritis and lipopeptide, a TLR2 agonist expressed by bacteria has been shown to intensify glomerulonephritis by activating TLR2." (PMID 32079183, 2020). "In summary, we have shown that the expression of TLR2 is increased on selected lymphocyte subsets in patients with glomerulonephritis, and particularly PGN." (PMID 32079183, 2020). "Our results suggest that TLR2 plays a role in glomerulonephritis, and particularly in PGN diseases." (PMID 32079183, 2020). "In this study we have demonstrated that neither TLR2 nor TLR4 deficiency modulates autoantibody production or glomerulonephritis in MRLlpr mice." (PMID 24086313, 2013).
glomerulosclerosis (3 papers, 2014 to 2021). A hardening of the kidney glomerulus caused by scarring of the blood vessels. "We recently reported that the glomerular endothelium expresses TLR2/4 in diabetic mice, and that the TLR2/4-ligand P. gingivalis LPS is a cause of glomerulosclerosis in diabetic mice with the accumulation of type 1 collagen and inflammatory cytokines in the glomeruli." (PMID 34425759, 2021). "It is thought that glomerular endothelium plays the principal role with TLR2 and 4 in glomerulosclerosis." (PMID 24835775, 2014). "We recently reported that the glomerular endothelium of diabetic mice expresses TLR2 and TLR4, and that the TLR2/4-ligand P. gingivalis LPS causes glomerulosclerosis in diabetic mice with the accumulation of type 1 collagen and inflammatory cytokines in glomeruli." (PMID 33407253, 2021).
hepatitis C (3 papers, 2010 to 2011). "Specific activation of TLR-2 in hepatitis C and homo- or heterodimerization with TLR-1 or TLR-6 has been shown; also, when these are blocked a significant decrease on production of proinflammatory cytokines appears, suggesting that some proteins produced by hepatitis C activate innate immune." (PMID 22114589, 2011).
infectious mononucleosis (3 papers, 2016 to 2020). A condition characterized by an increase in mononuclear white blood cells and swollen lymph nodes, which is usually caused by infection with the Epstein-Barr virus. "Pie charts show the percentage distribution of the mononucleosis symptoms in patients with the TLR2 2029C/T and the TLR9 1174G/A SNPs." (PMID 32753695, 2020). "In this study, we investigated whether CMV mononucleosis was associated with improper TLR functional responses and/or to the presence of SNPs within TLRs selected for their possible functional effects (TLR2 Arg753Gln; TLR3 Pro554Ser; TLR4 Asp299Gly; TLR7 Gln11Leu, and TLR9−1237 T/C)." (PMID 32850485, 2020).